RNU6-908P (RNA, U6 small nuclear 908, pseudogene)
Gene: Small nuclear RNA gene on chromosome 10 (29,711,915 to 29,712,008, forward strand). Ensembl gene ENSG00000222092.
Homologues: Orthologues: chimpanzee U6 (98% identical), macaque U6 (76% identical), dog U6 (73% identical), rabbit U6 (73% identical), pig U6 (72% identical), guinea pig U6 (68% identical). Paralogues in human: RNU6-641P (83% identical), RNU6-1316P (82% identical), RNU6-25P (82% identical), RNU6-29P (82% identical), RNU6-35P (82% identical), RNU6-1 (81% identical), RNU6-1099P (81% identical), RNU6-1124P (81% identical), RNU6-1145P (81% identical), RNU6-140P (81% identical), RNU6-2 (81% identical), RNU6-20P (81% identical), and 1284 more.